ATRIP (ATR interacting protein)
Description:
Required for checkpoint signaling after DNA damage. Required for ATR expression, possibly by stabilizing the protein.
Synonyms: FLJ12343; MGC20625; MGC21482; MGC26740; ATRIP-TREX1
Tractability: Small molecule: a high-quality ligand is known. PROTAC: ubiquitination databases record sites on it; its protein half-life has been measured; a small molecule that binds it is known.
Gene: Protein-coding gene on chromosome 3 (48,446,710 to 48,467,645, forward strand). Ensembl gene ENSG00000164053.
Subcellular location: Nucleus
Subcellular location (Human Protein Atlas): Nucleoplasm
Pathways (Reactome):
DNA Repair: Fanconi Anemia Pathway; HDR through Single Strand Annealing (SSA); Presynaptic phase of homologous DNA pairing and strand exchange; Processing of DNA double-strand break ends
Cell Cycle: Activation of ATR in response to replication stress; G2/M DNA damage checkpoint
Disease: Impaired BRCA2 binding to RAD51
Gene Ontology:
Molecular function: K63-linked polyubiquitin modification-dependent protein binding; protein binding
Biological process: DNA damage checkpoint signaling; DNA repair; regulation of double-strand break repair
Cellular component: ATR-ATRIP complex; nucleoplasm; nucleus
Genetic constraint (gnomAD): Loss-of-function variants: 41 observed, 75.23 expected, observed/expected ratio (o/e) 0.55, 90% interval 0.42 to 0.71. The upper end of that interval is the gene's LOEUF score, 0.71, which puts it in group 2 of 6, group 1 being the genes least tolerant of losing a copy. Missense variants: 917 observed, 952.45 expected, observed/expected ratio (o/e) 0.96, 90% interval 0.91 to 1.02. Synonymous variants: 380 observed, 399.4 expected, observed/expected ratio (o/e) 0.95, 90% interval 0.87 to 1.04.
Gene-disease validity (ClinGen):
ClinGen rates the evidence that ATRIP causes each of these diseases.
hereditary breast carcinoma (autosomal dominant): Limited. Breast carcinoma that has developed in relatives of patients with history of breast carcinoma.
Homologues: Orthologues: chimpanzee ATRIP (99% identical), macaque ATRIP (97% identical), dog ATRIP (84% identical), pig ATRIP (83% identical), rabbit ATRIP (82% identical), guinea pig ATRIP (77% identical), mouse Atrip (74% identical), rat Atrip (74% identical), tropical clawed frog atrip (41% identical).